ASB2 (ankyrin repeat and SOCS box containing 2)
Description:
Substrate-recognition component of a SCF-like ECS (Elongin-Cullin-SOCS-box protein) E3 ubiquitin-protein ligase complex which mediates the ubiquitination and subsequent proteasomal degradation of target proteins. Mediates Notch-induced ubiquitination and degradation of substrates including TCF3/E2A and JAK2. Required during embryonic heart development for complete heart looping (By similarity). Required for cardiomyocyte differentiation. Specifically promotes the ubiquitination of SMAD9 and targets it for proteasomal degradation, leading to avoid excessive accumulation of SMAD9. Plays a role in the regulation of NK-cell migration by modulating protein levels of filamin A/FLNA via regulation of its ubiquitination and proteasome degradation (By similarity). [Isoform 1]: Involved in myogenic differentiation and targets filamin FLNB for proteasomal degradation but not filamin FLNA. Also targets DES for proteasomal degradation (By similarity). Acts as a negative regulator of skeletal muscle mass (By similarity). [Isoform 2]: Targets filamins FLNA and FLNB for proteasomal degradation. This leads to enhanced adhesion of hematopoietic cells to fibronectin. Required for FLNA degradation in immature cardiomyocytes which is necessary for actin cytoskeleton remodeling, leading to proper organization of myofibrils and function of mature cardiomyocytes (By similarity). Required for degradation of FLNA and FLNB in immature dendritic cells (DC) which enhances immature DC migration by promoting DC podosome formation and DC-mediated degradation of the extracellular matrix (By similarity). Does not promote proteasomal degradation of tyrosine-protein kinases JAK1 or JAK2 in hematopoietic cells.
Synonyms: ASB-2
Tractability: PROTAC: UniProt records ubiquitination sites on it; ubiquitination databases record sites on it.
Gene: Protein-coding gene on chromosome 14 (93,933,783 to 93,978,831, reverse strand). Ensembl gene ENSG00000100628.
Subcellular location: Cytoplasm, cytoskeleton, stress fiber; Cytoplasm, myofibril, sarcomere, Z line (Isoform 1)
Subcellular location (Human Protein Atlas): Nucleoli fibrillar center; Cytosol; Nucleoplasm
Pathways (Reactome):
Immune System: Antigen processing: Ubiquitination & Proteasome degradation
Metabolism of proteins: Neddylation
Gene Ontology:
Molecular function: cullin family protein binding; protein binding; ubiquitin protein ligase activity
Biological process: cardiac muscle cell differentiation; proteasome-mediated ubiquitin-dependent protein catabolic process; protein ubiquitination; actin cytoskeleton organization; cardiac muscle cell development; dendritic cell migration; podosome assembly; regulation of barbed-end actin filament capping; signal transduction; heart looping; intracellular signal transduction
Cellular component: ubiquitin ligase complex; cytoplasm; cytosol; nucleus; stress fiber; Z disc
Genetic constraint (gnomAD): Loss-of-function variants: 55 observed, 55.38 expected, observed/expected ratio (o/e) 0.99, 90% interval 0.8 to 1.24. The upper end of that interval is the gene's LOEUF score, 1.24, which puts it in group 5 of 6, group 1 being the genes least tolerant of losing a copy. Missense variants: 899 observed, 856.63 expected, observed/expected ratio (o/e) 1.05, 90% interval 0.99 to 1.11. Synonymous variants: 371 observed, 367.12 expected, observed/expected ratio (o/e) 1.01, 90% interval 0.93 to 1.1.
Homologues: Orthologues: chimpanzee ASB2 (99% identical), macaque ASB2 (90% identical), mouse Asb2 (90% identical), guinea pig ASB2 (88% identical), dog ASB2 (87% identical), pig ASB2 (85% identical), rat Asb2 (83% identical), rabbit ASB2 (83% identical), tropical clawed frog asb2 (63% identical), zebrafish asb2a.1 (52% identical). Paralogues in human: UACA (21% identical), ANKRD24 (17% identical).
Diseases named in the same sentence as ASB2 in open-access papers:
ASB2 is named in the same sentence as 40 diseases in open-access papers, as found by Europe PMC text mining. Sharing a sentence is not in itself a finding about the gene and the disease. The quoted sentences say what the papers report.
acute myeloid leukemia (21 papers, 2019 to 2025). Acute myeloid leukemia (AML) is a group of neoplasms arising from precursor cells committed to the myeloid cell-line differentiation. "The demethyltransferase FTO has been found to exert a pro-carcinogenic effect in acute myeloid leukemia by regulating m6A levels on the mRNA of downstream target genes, such as ASB2 and RARA22." (PMID 37576401, 2023). "FTO played an oncogenic role in acute myeloid leukemia through regulating target genes such as ASB2 and RARA by reducing m6A levels in these mRNA transcripts." (PMID 32111213, 2020). "In a landmark study, overexpression of FTO promoted leukemia progression and inhibited all-trans-retinoic acid-induced acute myeloid leukemia (AML) differentiation by reducing m6A levels in ASB2 and RARA mRNA." (PMID 37916161, 2023). "For instance, the overexpression of FTO in acute myeloid leukemia (AML) can inhibit the m6A levels of Ankyrin repeat and SOCS box containing 2 (ASB2) and of retinoic acid receptor α (RARα) mRNA, resulting in the occurrence and progression of AML." (PMID 33643384, 2021). "FTO acted as an oncogene in acute myeloid leukemia (AML) through regulating target genes such as ASB2 and RARA by reducing m6A levels in these mRNA transcripts." (PMID 32209098, 2020). "Previous study reported that FTO was highly expressed and functioned as an oncogene in certain subtypes of acute myeloid leukemia (AML) by targeting ASB2 and RARA through mRNA demethylation." (PMID 31143705, 2019). "For instance, in acute myeloid leukemia, FTO eradicated the m6A modification from ASB2 and RAR-α mRNAs, leading to their degradation and thus suppressing myeloid differentiation." (PMID 38556586, 2024). "In acute myeloid leukemia, FTO was shown to control stem cell differentiation through the ASB2/RARA axis, and FTO was revealed to affect immunotherapy by regulating intracellular factors (PD-1, CXCR4, and SOX10) in melanoma." (PMID 38384328, 2024). "FTO can downregulate the expression of ASB2 and RARA by reducing m6A levels in UTRs of transcripts, resulting in the inhibition of ATRA-mediated acute myeloid leukemia (AML) cell differentiation." (PMID 37178254, 2023). "Studies have reported its high expression in acute myeloid leukemia (AML), promoting cellular transformation and proliferation by the post-transcriptional regulation of ASB2, RARA, MYC, and CEBPA." (PMID 36371254, 2022). "FTO downregulates m6A levels, modulates the expression of Ankyrin Repeat and SOCS Box Containing 2 (ASB2) and Retinoic Acid Receptor Alpha (RARA), enhances gene-mediated cell transformation and leukemia onset, and inhibits acute myeloid leukemia (AML) cell differentiation." (PMID 38711100, 2024). "Moreover, FTO promotes proliferation of AML cells through targeting of the ASB2 and RARA in acute myeloid leukemia cells." (PMID 31333841, 2019). "In specific subtypes of acute myeloid leukemia (AML), elevated FTO levels decrease m6A levels in ASB2 and RARA mRNA transcripts, thereby promoting their expression." (PMID 40000966, 2025). "m6A demethylase FTO is highly expressed and plays a critical oncogenic role in acute myeloid leukemia (AML) by targeting a cohort of critical transcripts, such as ankyrin repeat and SOCS box-containing 2 (ASB2) and retinoic acid receptor alpha (RARA)." (PMID 36835633, 2023). "FTO can downregulate the expression of ASB2 and retinoic acid receptor alpha (RARA) by reducing m6A levels in UTRs of transcripts, resulting in the inhibition of all-trans retinoic acid (ATRA)-mediated acute myeloid leukemia (AML) cell differentiation." (PMID 37151887, 2023).
leukemia (16 papers, 2016 to 2024). A malignant (clonal) hematologic disorder, involving hematopoietic stem cells and characterized by the presence of primitive or atypical myeloid or lymphoid cells in the bone marrow and the blood. "The use of small-molecule inhibitors targeting FTO affected the expression levels of downstream genes such as MYC, CEBPA, RARA, and ASB2, thereby exerting anti-leukaemia effects." (PMID 39641872, 2024). "ASB2 is an E3 ubiquitin-protein ligase which can inhibit growth and chromatin condensation to inhibit the occurrence and development of leukemia." (PMID 36611207, 2023). "Upon treatment with retinoic acid, which has a force de novo differentiation in leukemia cells, ASB2 is up-regulated and induces growth inhibition and chromatin condensation." (PMID 34439361, 2021). "MLL2 target genes, profiling in both wild-type and MLL2 null mammalian colon cancer cells (HCT116 cells), revealed that MLL2 promotes retinoic acid-responsive gene transcription such as ASB2 which was previously induced in leukemia cells." (PMID 34440566, 2021). "By regulating the expression of the leukemia-related oncogenes ASB2 and RARA, FTO overexpression can downregulate the total level of m6A, promote cell growth and colony formation in vitro, and promote the occurrence of leukemia in vivo." (PMID 34381710, 2021). "Among the genes associated with MLL2-enriched loci was the Ankyrin repeat and SOCS box protein 2 (ASB2) which in previous studies had been demonstrated to be induced by retinoic acid in leukemia cells." (PMID 34440566, 2021). "Knockdown of ASB2 in leukemia cells delays RA-induced differentiation, which suggests that ASB2 regulates hematopoietic cell differentiation by targeting filamins for degradation, thereby modulating actin remodeling." (PMID 27030794, 2016). "FTO enhances leukemogenesis and leukemia oncogene-mediated cell transformation by reducing m6A levels on mRNA transcripts of targets such as ASB2 and RARA, thereby regulating their expression and inhibiting all-trans retinoic acid (ATRA)-induced differentiation of AML cells." (PMID 39295872, 2024). "ASB2 (ankyrin repeat and SOCS box containing 2) and RARA (retinoic acid receptor alpha) are induced during hematopoiesis and function as crucial regulators of ATRA-induced differentiation of leukemia cells." (PMID 29439529, 2018). "In leukemia, FTO promoted the proliferation of AML cells by reducing m6A levels at the 3′-UTR of Asb2 and 3′ and 5′-UTR of Rara, two mediators of hematopoiesis and differentiation, resulting in decreased ASB2 and RARA protein expression." (PMID 35350378, 2022).
myeloid leukemia (3 papers, 2012 to 2021). A clonal proliferation of myeloid cells and their precursors in the bone marrow, peripheral blood, and spleen. "This together with the fact that ASB2α knockdown in myeloid leukemia cells delays retinoic acid-induced differentiation indicate that ASB2 is one of the genes associated with induced-differentiation of myeloid leukemia cells." (PMID 22916308, 2012). "ASB2 is induced by retinoic acid (RA) in acute promyelocytic leukemia cells, and exogenous ASB-2 in myeloid leukemia cells results in growth inhibition and chromatin condensation, which recapitulate the early steps of induced differentiation of acute promyelocytic leukemia cells." (PMID 27030794, 2016).
myotonic dystrophy type 1 (3 papers, 2018 to 2021). Steinert disease, also known as myotonic dystrophy type 1, is a muscle disease characterized by myotonia and by multiorgan damage that combines various degrees of muscle weakness, arrhythmia and/or cardiac conduction disorders, cataract, endocrine damage, sleep disorders and baldness. "As elevated ASB2 has been associated with the pathological phenotype of type 1 myotonic dystrophy, the findings reported herein may offer insight into pathological processes of relevance to this condition." (PMID 33516941, 2021).
endometrial cancer (2 papers, 2023 to 2025). Primary or metastatic malignant neoplasm involving the endometrium (mucous membrane that lines the endometrial cavity). "Through experiments, it discussed for the first time the expression and anti-cancer effects of ASB2 in endometrial cancer." (PMID 40356925, 2025). "As the expression of ASB2 significantly decreases during the progression from normal tissue to endometrial cancer, it is difficult to attribute the drastic decrease solely to the consumption of immune cells." (PMID 40356925, 2025). "The study preliminarily confirmed the anti-cancer effect of ASB2 in endometrial cancer cell lines through experiments and suggested its correlation with being a protective prognostic factor." (PMID 40356925, 2025). "Although previous studies have found that the expression level of ASB2 in EC is lower than that in normal tissues, which implies that upregulating the expression of ASB2 is a potential therapeutic strategy for endometrial cancer." (PMID 40356925, 2025). "In this study, ASB2 expression levels in endometrial cancer tissues were found to be lower than those in normal tissues, and it was found to be a protective gene." (PMID 36611207, 2023). "In summary, downregulating UBE2S expression or upregulating ASB2 expression in tumors is a potential treatment strategy for endometrial cancer." (PMID 36611207, 2023). "Therefore, up-regulation of ASB2 expression is a potential treatment strategy for endometrial cancer." (PMID 36611207, 2023).
lung carcinoma (2 papers, 2021 to 2022). "GNG7, MXRA7, ASB2, and CHMP4C are also involved in the development of lung cancer, gastric cancer, colorectal cancer, and cervical cancer, respectively." (PMID 36225190, 2022).
Obesity (2 papers, 2022 to 2025). Accumulation of substantial excess body fat. "Overall, these results suggest a mild improvement in whole‐body insulin sensitivity in Asb2 MKO mice, although the augmented muscle mass was insufficient to counteract HFD‐induced obesity or glucose intolerance." (PMID 40641155, 2025).
T-cell acute lymphoblastic leukemia (2 papers, 2021 to 2024). Acute lymphoblastic leukemia of T-cell origin. "ASB2, regulated by Notch1, promotes NF-κB activation in T-cell acute lymphoblastic leukemia, and based on a genetic screen, it is a putative DLBCL essential gene." (PMID 34763718, 2021).
age (1 paper, 2025). A temporal measurement of the time period elapsed since an identifiable point in the life cycle of an organism. "Additionally, we investigate the long‐term effects of Asb2 on aged muscle, underlying mechanisms on muscle regulation and metabolic effects of Asb2 MKO mice to better understand its role in muscle function and age‐related metabolic diseases." (PMID 40641155, 2025).
colon cancer (1 paper, 2024). "In colon cancer cells lacking MLL2 expression, the target gene expression spectrum of MLL2 revealed its role in promoting transcription of retinoic acid reactive genes such as ASB2." (PMID 38903727, 2024).
dilated cardiomyopathy (1 paper, 2020). Cardiomyopathy which is characterized by dilation and contractile dysfunction of the left and right ventricles. "Asb2 was also demonstrated to ubiquitylate talin-1 (Tln1), a protein that is together with talin-2 required for myoblast fusion and sarcomere assembly of skeletal muscles, and whose loss results in costameric instability and dilated cardiomyopathy in hearts." (PMID 33114658, 2020). "Similar to the cullin-1 substrate adapter Fbxo40, hearts of mice that lack Prmt1 suffer from dilated cardiomyopathy and show aberrant Asb2 splicing." (PMID 33114658, 2020).
hypertrophic cardiomyopathy (1 paper, 2020). A condition in which the myocardium is hypertrophied without an obvious cause. "ASB2 is abnormally downregulated in a mouse model for hypertrophic cardiomyopathy with an associated buildup of desmin levels due to loss of ASB2-directed proteosomal-mediated degradation in cardiomyocytes." (PMID 34968235, 2020).
Mitochondrial myopathy (1 paper, 2025). "Unlike MKO mice in which the Asb2 gene is deleted from birth, the reduced expression of the Asb2 gene observed in muscles affected by primary conditions such as myotonic dystrophy or mitochondrial myopathy may represent a compensatory mechanism aimed at protecting against muscle loss." (PMID 40641155, 2025).
myotonic dystrophy (1 paper, 2025). An inherited progressive disorder affecting the muscles. "There was a positive correlation between Asb2 expression and lean body mass in individual Polg mut mice, similar to that observed in human myotonic dystrophy." (PMID 40641155, 2025).
myotonic dystrophy type 2 (1 paper, 2025). Myotonic dystrophy type 2 (MD2), also known as proximal myotonic myopathy, is a very rare genetic multi-system disorder of late childhood or adult-onset characterized by mild myotonia, muscle weakness, and rarely cardiac conduction disorders. "The clinical relevance of Asb2 has been evident in the Gene Expression Omnibus (GEO) database, but contrary to our expectation, Asb2 expression was decreased in the vastus lateralis skeletal muscles of patients with myotonic dystrophy type 2 (GEO accession GDS5276)." (PMID 40641155, 2025).
prostate tumors (1 paper, 2019). "All genes except ASB2 exhibited significantly increased tumor methylation as compared to normal prostate in all significant proximal probes, while ASB2 methylation was significantly decreased in TCGA prostate tumors at all significant probes within the promoter as well as its single proximal probe." (PMID 30917865, 2019). "Promoter methylation gain of one such promising candidate gene, ankyrin repeat and SOCS-box containing protein 2 (ASB2), within the TET2-target site is investigated in an independent series of primary prostate tumors." (PMID 30917865, 2019). "Decreased expression of these genes significantly discriminates between recurrent and non-recurrent prostate tumors from the Cancer Genome Atlas (TCGA) cohort (n = 423), and ASB2, NUDT10, and SRPX were significantly correlated with lower recurrence-free survival in patients by Kaplan-Meier analysis." (PMID 30917865, 2019).
sarcopenia (1 paper, 2025). Progressive decline in muscle mass due to aging which results in decreased functional capacity of muscles. "Collectively, these findings suggest that targeting Asb2 in a skeletal muscle‐specific manner may offer a novel therapeutic strategy to combat sarcopenia by promoting both skeletal muscle mass and strength." (PMID 40641155, 2025). "Cell death and apoptosis are increasing features of sarcopenia and muscle atrophy; thus, downregulation of these processes could explain the phenotypes observed in Asb2 MKO muscle." (PMID 40641155, 2025). "Overall, these results suggest that muscle‐specific deletion of Asb2 leads to an increase in muscle size at a young age and maintains increased muscle mass and strength at an old age in both sexes, indicating a potent preventive role against sarcopenia in vivo." (PMID 40641155, 2025). "First, we could not assess the role of Asb2 deletion at 24 months of age, when sarcopenia becomes more prominent." (PMID 40641155, 2025).